ASPDH (aspartate dehydrogenase domain containing)
Tractability: No criterion of Open Targets' tractability assessment is met for any kind of drug.
Gene: Protein-coding gene on chromosome 19 (50,511,568 to 50,514,690, reverse strand). Ensembl gene ENSG00000204653.
Subcellular location (Human Protein Atlas): Nucleoplasm; Cytosol
Gene Ontology:
Molecular function: aspartate dehydrogenase [NAD(P)+] activity; NADP binding; oxidoreductase activity
Biological process: NAD+ biosynthetic process
Genetic constraint (gnomAD): Loss-of-function variants: 25 observed, 28.72 expected, observed/expected ratio (o/e) 0.87, 90% interval 0.63 to 1.22. The upper end of that interval is the gene's LOEUF score, 1.22, which puts it in group 5 of 6, group 1 being the genes least tolerant of losing a copy. Missense variants: 401 observed, 361.74 expected, observed/expected ratio (o/e) 1.11, 90% interval 1.02 to 1.2. Synonymous variants: 168 observed, 153.74 expected, observed/expected ratio (o/e) 1.09, 90% interval 0.96 to 1.24.
Homologues: Orthologues: chimpanzee ASPDH (99% identical), macaque ASPDH (94% identical), mouse Aspdh (88% identical), dog ASPDH (87% identical), pig ASPDH (87% identical), guinea pig ASPDH (86% identical), rat Aspdh (86% identical), tropical clawed frog aspdh (49% identical), zebrafish aspdh (47% identical), Caenorhabditis elegans F17C8.9 (43% identical).
Diseases named in the same sentence as ASPDH in open-access papers:
ASPDH is named in the same sentence as 4 diseases in open-access papers, as found by Europe PMC text mining. Sharing a sentence is not in itself a finding about the gene and the disease. The quoted sentences say what the papers report.
glioma (1 paper, 2024). A benign or malignant brain and spinal cord tumor that arises from glial cells (astrocytes, oligodendrocytes, ependymal cells). "Correlation analysis revealed that TSPAN4 was positively correlated with ITGB1, GDF15, ITGA3 and ITGA6, and negatively correlated with CHD7, ASPDH, TMEM8B and GHITM in glioma." (PMID 39723210, 2024).
ASPDH also shares sentences with these, for which no sentence is quoted: liver cancer (1 paper); Stroke (1); tumor (1).